NDUFAF3 (NADH:ubiquinone oxidoreductase complex assembly factor 3)
Description:
Essential factor for the assembly of mitochondrial NADH:ubiquinone oxidoreductase complex (complex I).
Synonyms: C3orf60; MGC10527; DKFZP564J0123; E3-3; 2P1; MC1DN18
Tractability: Small molecule: an approved drug acts on it. PROTAC: its protein half-life has been measured.
Gene: Protein-coding gene on chromosome 3 (49,020,459 to 49,023,495, forward strand). Ensembl gene ENSG00000178057.
Subcellular location: Nucleus; Mitochondrion inner membrane
Pathways (Reactome):
Metabolism: Complex I biogenesis
Gene Ontology:
Molecular function: protein binding
Biological process: mitochondrial respiratory chain complex I assembly
Cellular component: mitochondrial inner membrane; mitochondrion; nucleus
Genetic constraint (gnomAD): Loss-of-function variants: 22 observed, 25.75 expected, observed/expected ratio (o/e) 0.85, 90% interval 0.61 to 1.22. The upper end of that interval is the gene's LOEUF score, 1.22, which puts it in group 5 of 6, group 1 being the genes least tolerant of losing a copy. Missense variants: 251 observed, 262.03 expected, observed/expected ratio (o/e) 0.96, 90% interval 0.86 to 1.06. Synonymous variants: 113 observed, 109.63 expected, observed/expected ratio (o/e) 1.03, 90% interval 0.88 to 1.21.
Gene-disease validity (ClinGen):
ClinGen rates the evidence that NDUFAF3 causes each of these diseases.
mitochondrial disease (autosomal recessive): Definitive.
Homologues: Orthologues: chimpanzee NDUFAF3 (99% identical), macaque NDUFAF3 (96% identical), pig NDUFAF3 (84% identical), dog NDUFAF3 (84% identical), rabbit NDUFAF3 (84% identical), guinea pig NDUFAF3 (80% identical), mouse Ndufaf3 (80% identical), rat Ndufaf3 (79% identical), zebrafish ndufaf3 (54% identical), tropical clawed frog ndufaf3 (53% identical), Drosophila melanogaster CG5569 (35% identical), Caenorhabditis elegans nuaf-3 (34% identical).
Diseases named in the same sentence as NDUFAF3 in open-access papers:
NDUFAF3 is named in the same sentence as 17 diseases in open-access papers, as found by Europe PMC text mining. Sharing a sentence is not in itself a finding about the gene and the disease. The quoted sentences say what the papers report.
type 2 diabetes (3 papers, 2020 to 2024). "The protein NDUFAF3 encodes is targeted by metformin, the first-line drug for treating type 2 diabetes." (PMID 38177345, 2024).
COVID-19 (1 paper, 2022). A disease caused by infection with severe acute respiratory syndrome coronavirus 2. "Additionally, we found 44, 42, and 53 up-DEGs that were notably associated with mild, moderate, and severe COVID-19, and there were six significant common genes across three phases of COVID-19, including TCF7, GZMH, RAB5IF, CCND2, BIRC6, and NDUFAF3." (PMID 35172892, 2022).
Leigh syndrome (1 paper, 2025). A progressive neurological disease defined by specific neuropathological features associating brainstem and basal ganglia lesions. "Moreover, some of the genes that were downregulated in the absence of IRF-5, like Ndufaf3 and Coq4, are associated with mitochondrial disorders in humans and with the Leigh syndrome." (PMID 40494997, 2025).
myocarditis (1 paper, 2024). Myocarditis is a condition that is characterized by inflammation of the heart muscle (myocardium). "Interestingly, ERRα bound Ndufaf3 and Sdhaf1 more significantly in females with myocarditis compared to males with no prediction for these genes by RNAseq or TRANSFAC." (PMID 39696682, 2024).
myoclonic epilepsy (1 paper, 2018). A group of epilepsy syndromes in which myoclonic seizures are a prominent feature. "Mutations in NDUFAF3/C3ORF60 were found in three families with CI deficiency associated with a spectrum of severe phenotypes: a fulminant syndrome dominated by muscle hypertonia in the first, macrocephaly and severe muscle weakness in the second, myoclonic epilepsy and leukomalacia in the third." (PMID 30030362, 2018).
Usher syndrome (1 paper, 2021). A syndromic diseae characterized by the association of sensorineural deafness (usually congenital) with retinitis pigmentosa and progressive vision loss. "This includes a variant of unknown significance (VUS) in CDH23 (c.5653CT), previously reported as a VUS in a case with Usher Syndrome, and a ClinVar reported pathogenic variant in NDUFAF3 (c.188dupA), a gene associated with Mitochondrial complex I deficiency, nuclear type 18." (PMID 34828371, 2021).
mitochondrial disease (2 papers, 2009 to 2025). "Since we first compiled the list of putative genes, three were identified as causing mitochondrial disease in patients (C20orf7, CoQ9 and NDUFAF3)." (PMID 19852779, 2009). "Late detection of assembly factors with severe phenotype includes genes such as NDUFAF3, SURF1, TACO1, SCO1, LYRM7, or TIMMDC1, whose mutations are commonly found in patients with mitochondrial diseases (Fig. EV2F)." (PMID 40301572, 2025).
brain disorder (1 paper, 2024). A disease affecting the brain or part of the brain. "We found 7 variants that were associated with neurodevelopment and brain disorders, of which, 4 variants were found in both patients, namely in genes CTBP2, CDC27, UNC13D and IRF8, and 3 variants found in either of the patients, NDUFAF3, MRPS25, MORC3." (PMID 38638145, 2024).
NDUFAF3 also shares sentences with these, for which no sentence is quoted: breast carcinoma (3 papers); Type 1 diabetes (2); cancer (1); diabetes (1); Hypertension (1); lymph node metastasis (1); musculoskeletal system diseases (1); neurological disease (1); tumor (1).